AHRR (aryl hydrocarbon receptor repressor)
Diseases named in the same sentence as AHRR in open-access papers (continued):
Sharing a sentence is not in itself a finding about the gene and the disease.
lung carcinoma (continued). "AhRR hypermethylation and its subsequent silencing is reported to be involved in enhanced growth potential in lung cancer cells; moreover, its repression may also lead to an aggressive tumorigenic phenotype." (PMID 37511212, 2023). "AHRR hypomethylation is also associated with lung cancer and, interestingly, predicts lung cancer diagnosis independent of smoking status." (PMID 37691855, 2023). "This could inspire similar studies in a broader context and should be taken into account before clinical implementation of AHRR methylation as a biomarker, for example to improve eligibility assessment for lung cancer screening." (PMID 37691855, 2023). "The inactivation of the AHR-pathway, possibly initiated and mediated by hypomethylation and overexpression of AHRR, could be an important early step in lung cancer development." (PMID 32963246, 2020). "Since both cigarette smoke and PM2.5 are inhalable carcinogens rich in PAH, PM2.5-induced AHRR methylation might also explain the pathophysiological mechanism of lung cancer." (PMID 32736658, 2020). "In addition, our results showed that the elevated expressions of AHRR and GPR15 were associated with smoking-altered hypomethylations of cg14817490 and cg19859270 in both lung cancer blood and tumor tissues, respectively." (PMID 32928150, 2020). "Since cigarette smoke contains PAHs, it has been hypothesized that decreased AHRR methylation induced by cigarette smoking may be a mediator in lung cancer development." (PMID 32962699, 2020). "Association between AHRR (cg05575921) methylation extent in quantiles (%) and reduced survival (from all-cause mortality) in 461 matched individuals without lung cancer." (PMID 30730943, 2019). "In order to further investigate the lack of association between AHRR methylation extent and reduced survival in lung cancer patients, we also analyzed the association in individuals without lung cancer." (PMID 30730943, 2019). "AHRR (cg05575921) methylation is linked to smoking but does not provide independent prognostic information in lung cancer patients." (PMID 30730943, 2019). "Specifically, our work points towards inactivation of the AHR pathway as the more fundamental event underlying smoking-mediated lung carcinogenesis, instead of AHRR hypomethylation which is not observed in lung cancer." (PMID 29262847, 2017). "Lung cancer patients had significantly more hypomethylated AHRR and F2RL3 compared to controls." (PMID 28453567, 2017). "The main question arising from our previous studies of healthy subjects was whether methylation changes in the AHRR and F2RL3 genes are causally involved in lung cancer aetiology by mediating the risk induced by tobacco smoking." (PMID 26667048, 2015). "In a recent case–control study (N=552 pairs) lower methylation of both AHRR CpG3 and F2RL3 CpG2 in blood was associated with higher risk of lung cancer and the authors proposed that DNA methylation of the two studied CpG sites might be a predictor of future lung cancer." (PMID 34570895, 2022). "We found no causal association between methylation of AHRR and lung cancer or COPD." (PMID 33752734, 2021). "Further, since AHRR methylation only reverts very slowly over decades after smoking cessation, the prognostic benefit from quitting within years before blood sampling, cannot be monitored by measuring AHRR methylation, especially in cohorts with poor short-term prognosis, i.e. lung cancer patients." (PMID 30730943, 2019). "Logistic multivariate analysis showed that AHRR methylation was significantly associated with the risk of lung cancer (OR = 0.96), but cotinine was not (OR = 1.02) although univariate analysis showed that cotinine was significantly associated with the risk of lung cancer." (PMID 28453567, 2017).
lung carcinoma (continued). "Mediation analysis of methylation at these two specific CpG sites in AHRR and F2RL3 estimated that approximately 37% (95% CI: 19–66%) of the total effect of tobacco smoking on lung cancer odds is mediated by methylation at these loci." (PMID 41516393, 2026). "A single measurement of AHRR methylation correlates with the risks of COPD, lung cancer, ischemic heart disease, and death." (PMID 36621758, 2023). "For example, the methylation status of AHRR, P16, F2RL3, and DAPK has been reported as a biomarker for evaluating the progression of smoking-related diseases, such as lung cancer." (PMID 34785774, 2022). "Despite its limitations, our study demonstrates that AHRR, 6p21.33, and F2RL3 methylation individually are strong predictors for lung cancer development." (PMID 27924164, 2016). "AHRR (cg05575921) methylation cannot be used to predict smoking mediated reduced survival in lung cancer patients." (PMID 30730943, 2019). "AHRR (cg05575921) methylation might serve as an indicator of differential exposures to PM2.5 and lung cancer which is also a PM2.5-related disease." (PMID 31060609, 2019). "Further, we found that AHRR hypomethylation behaves different on reduced survival in lung cancer patients than in individuals without lung cancer." (PMID 30730943, 2019). "Consistent with this, many of the top-ranked hypomethylated smkDMCs, including those mapping to the AHRR locus, do not exhibit hypomethylation in lung cancer, suggesting that cells carrying these DNAm alterations are not selected for during cancer progression." (PMID 29262847, 2017). "We identify TFs, such as AHR, which become inactivated in the earliest stages of lung cancer and which, unlike AHRR hypomethylation, are also inactivated in lung cancer itself." (PMID 29262847, 2017). "A prominent example is hypomethylation of the aryl hydrocarbon-receptor repressor (AHRR) locus, which is observed in blood and squamous epithelial cells of smokers, but not in lung cancer." (PMID 29262847, 2017). "In conclusion, this analysis suggests (i) that methylation of the smoking-related AHRR and F2RL3 CpG sites might be relevant to lung cancer aetiology and (ii) would explain approximately one-third of the risk increase induced by tobacco exposure." (PMID 26667048, 2015). "To bring some clarity to this question, we used mediation analysis to quantify the amount by which cg05575921 (AHRR gene) and cg03636183 (F2RL3 gene) methylation might mediate the effect of smoking on lung cancer incidence." (PMID 26667048, 2015). "Having reached this threshold, more intensive smoking reduces survival, but will not reduce methylation further as suggested by the very narrow range of AHRR methylation in the lung cancer patients compared with the matched individuals from the general population without lung cancer." (PMID 30730943, 2019). "Interestingly, while most of the NSCLC patients studied were current smokers, cancer cells with AhR and AhRR expression, which is activated by the many components/carcinogens of tobacco smoke and, therefore, may be used as a biomarker of lung cancer development, were not identified in our work." (PMID 39199657, 2024).
breast cancer (17 papers, 2010 to 2024). A primary or metastatic malignant neoplasm involving the breast. "In fact, AhR deficiency as well as AhRR overexpression resulted in an accumulation of these DNA lesions in both breast cancer cell-lines, suggesting a regulatory function of AhR in DSB repair." (PMID 33763068, 2021). "In favour of this hypothesis there are recent observations in breast cancer showing that high AHRR mRNA levels are associated with favourable metastasis-free survival." (PMID 38361045, 2024). "Notably, low level AHRR expression in breast cancer is associated with poorer survival and ectopic AHRR expression is associated with decreased invasion." (PMID 33396563, 2020). "In addition to a host-dependent tumor suppressive effect of AhRR indicated by current data from a mouse xenograft model, the results with mammary tumor cells suggest that AhRR mediates also cell-intrinsic responses associated with the suppression of C/EBPβ and COX-2." (PMID 33763068, 2021). "In human breast cancer, high expression of AhRR, the dedicated AhR repressor, independently predicts prolonged metastasis-free survival, in agreement with our findings in PyMT mice." (PMID 36588678, 2022). "The AhRR decreases availability of functional AhR by competing for ARNT, and using transgenic mice overexpressing AhRR, it was shown that AhRR suppresses mammary tumor development and AhR-dependent growth and the inflammatory gene COX2 (±TCDD)." (PMID 36428667, 2022). "While our results suggest that AhRR overexpression in the host environment is sufficient to decrease mammary tumor cell growth, the tumor cell-intrinsic vs. extrinsic roles of AhR/AhRR are complex and have to be explored in more detail." (PMID 33763068, 2021). "The results suggest that AhRR overexpression in the host environment is sufficient to inhibit orthotopic growth of mammary tumor cells." (PMID 33763068, 2021). "This study is the first to demonstrate that AhRR overexpression restricts mammary tumor cell growth and tumorigenesis in vivo." (PMID 33763068, 2021). "To examine the tumor-suppressive action of AhRR in vivo, we compared growth of syngeneic E0771 mammary tumor cells in the mammary fat pad of wildtype (wt) B6 and AhRR Tg mice." (PMID 33763068, 2021). "Further AhRR overexpression or knockout of AhR in human breast cancer cells enhanced apoptosis induced by chemotherapeutics and inhibited the growth of mouse mammary tumor cells." (PMID 33763068, 2021). "Results indicate a significantly suppressed growth of E0771 mammary tumor cells in AhRR Tg mice compared to wt mice." (PMID 33763068, 2021). "We report here that AhRR overexpression sensitizes PyMT-derived mammary tumor cells and human breast cancer cells to both Dox and EtOP." (PMID 33763068, 2021). "Expression analysis confirmed that AhR as well as COX-2 and C/EBPβ were suppressed in mammary tumors of PyMT/AhRR+ mice compared to PyMT/wt mice." (PMID 33763068, 2021). "Further, breast cancer patients who retain high AhRR expression show prolonged metastasis-free survival, strongly suggesting that AhRR plays a functional role in limiting biological behaviors which contribute to metastasis." (PMID 33763068, 2021). "Despite dysregulation of the AhR/AhRR axis in breast cancer, relatively little is known about the function of AhRR in vivo." (PMID 33763068, 2021). "Inversely, breast cancer patients with higher expression level of AHRR, ANKRD52, BCAR1, PANX2, hsa-miR-105-5p, hsa-miR-4435, and LINC01742 showed the lower OS." (PMID 34055638, 2021). "Support for the premise comes from a recent report, showing that breast cancer patients who had low AhRR expression also had shorter metastasis-free survival and identified AhRR as an independent prognostic factor." (PMID 33763068, 2021).
breast cancer (continued). "Using our previously characterized AhRR transgenic mouse, we demonstrate that AhRR overexpression restricts the growth of both E0771 mammary tumor cells and mammary tumors in the Polyoma Middle T antigen (PyMT) model of mammary tumorigenesis." (PMID 33763068, 2021). "To further examine the effect of AhRR on the expression of COX-2 and C/EBPβ and to test mammary tumor cell-intrinsic effects of AhRR overexpression, we utilized UCD-PYMT cells, a mammary tumor cell line previously established from PyMT mice." (PMID 33763068, 2021). "The results are in line with the in vivo findings and confirm previous reports showing a reduced cell proliferation, increased apoptosis and inhibition of inflammatory invasion and migration of breast cancer cells by AhRR overexpression." (PMID 33763068, 2021). "We find that expression changes in the AhR/AhRR axis observed in human breast cancer are reflected in this model, with overexpression of AhR and its canonical targets COX-2 and C/EBPβ along with down-regulation of AhRR." (PMID 33763068, 2021). "Using the AhRR transgenic mouse, we demonstrate that AhRR overexpression opposes AhR-driven and inflammation-induced growth of mammary tumors in two different murine models of breast cancer." (PMID 33763068, 2021). "In prior work, we demonstrated that overexpression of AhRR in vitro, in human breast cancer cells, inhibits cell survival mediated by AhR." (PMID 33763068, 2021). "TTP has also been demonstrated to be a post-transcriptional regulator of aryl hydrocarbon receptor repressor (AHRR) in breast cancer cells." (PMID 32545247, 2020). "The results confirm data with ectopic expression of AhRR in human breast cancer cells and previous reports showing that AhRR can act as a tumor suppressor against several types of cancers." (PMID 31035533, 2019). "In this study, we compared the genome-wide binding profiles of AHR and AHRR in MCF-7 human breast cancer cells treated for 24 h with TCDD using chromatin immunoprecipitation followed by next-generation sequencing (ChIP-Seq)." (PMID 28681081, 2018). "Relationship between AHRR mRNA expression and classical clinical and pathological parameters in a cohort of 439 breast cancers." (PMID 29320557, 2018). "AHRR has also been reported to function as a tumor suppressor in multiple types of cancer, including breast cancer." (PMID 28681081, 2018). "For example, in human mammary tumor cell lines, AHRR knock-down with siRNA enhances AHR activity, confirming the assumption that AHRR constitutively represses AHR activity in tumors." (PMID 22952704, 2012). "It was recently reported that AHRR is a putative new tumor suppressor gene in multiple types of human cancers including breast cancer." (PMID 20409316, 2010). "Our results suggest that AhRR may represent an independent prognosis factor in diffuse GC, as we previously reported for breast cancer." (PMID 39200369, 2024). "Similarly, the authors found that the overexpression of AhRR inhibited the growth of UCD-PyMT mammary tumor cells." (PMID 37106727, 2023). "This suggests that functional restoration of AhRR to breast cancer cells may be useful in addressing chemoresistance, a major driver of breast cancer mortality." (PMID 33763068, 2021). "In the current study we have examined several AhR-driven outcomes, to determine whether AhRR functionally opposes AhR and is able to suppress the development of mammary tumors." (PMID 33763068, 2021). "This study provides the first in vivo evidence that AhRR suppresses mammary tumor development and suggests that strategies which lead to its functional restoration and expression may have therapeutic benefit." (PMID 33763068, 2021). "Moreover, reports have shown that the AhRR suppresses growth of tumor cells including breast cancer cells in vitro." (PMID 33763068, 2021).
breast cancer (continued). "Furthermore, the tumor suppressive function of AhRR was confirmed in mouse PyMT-derived mammary tumor cells and human breast cancer cell lines indicating that AhRR inhibits cell proliferation and AhR-mediated apoptosis resistance." (PMID 33763068, 2021). "This analysis confirmed that AHRR mRNA level is an independent prognostic factor in breast cancer." (PMID 29320557, 2018). "Recently, lost or reduced expression of AHRR has been observed in many types of cancerous human tissue, including hepatocellular carcinoma, colon carcinoma, prostate cancer, breast cancer and others, demonstrating that AHRR is a putative new tumor suppressor gene in multiple types of human cancers." (PMID 22952704, 2012). "The results suggested that metastasis associated RNAs, including AHRR, TTC34, CNTRL, ANKRD52, BCAR1, TMEM151B, PANX2, hsa-miR-105-5p, hsa-miR-4435, hsa-miR-5691, hsa-miR-92a-1-5p, and LINC01742 could serve as the prognostic biomarkers of breast cancer patients." (PMID 34055638, 2021). "In the syngeneic E0771 model, we demonstrate that AhRR overexpression inhibits basal and AhR-driven (TCDD-stimulated) mammary tumor cell growth." (PMID 33763068, 2021). "To better understand the role and extent to which AHRR alters AHR action, we determined the genome-wide binding profiles of AHRR in MCF-7 human breast cancer cells using chromatin immunoprecipitation followed by next-generation sequencing (ChIP-Seq)." (PMID 28681081, 2018). "To identify the genomic binding profiles of AHR and AHRR, we performed ChIP-Seq on chromatin isolated from MCF-7 human breast cancer cells treated with 10 nM TCDD for 24 h." (PMID 28681081, 2018). "In an effort to better understand the AHR–AHRR signaling axis, we determined the genome-wide binding profiles of AHRR and AHR in TCDD-treated MCF-7 human breast cancer cells." (PMID 28681081, 2018). "In our recent study we demonstrated that overexpression of AhRR (Aryl Hydrocarbon Receptor Repressor) suppresses AhR-driven (TCDD-stimulated) growth of syngeneic mammary tumors as well the onset, growth and metastasis of spontaneous mammary tumors in PyMT mice." (PMID 36588678, 2022). "Further, we tested whether AhRR affects the expression of COX-2 and C/EBPβ as well as the growth of tumor cells in vitro using UCD-PYMT, a tumor cell line isolated from a PyMT mammary tumor." (PMID 33763068, 2021). "While the repressor protein of the AhR (AhRR) blocks the canonical AhR pathway, the function of AhRR in the development of breast cancer is not well-known." (PMID 33763068, 2021). "Moreover, experiments with luminal ER-positive MCF-7 cells were included to explore if AhRR also mediates apoptosis in non-TNBC breast cancer cells." (PMID 33763068, 2021). "The levels of AHR, AHR nuclear translocator (ARNT) and AHR repressor (AHRR) mRNA expression were analyzed in a cohort of 439 breast tumors, demonstrating a weak association between high AHR expression and age greater than fifty years and ERα-negative status, and HR-/ERBB2 breast cancer subtypes." (PMID 29320557, 2018).
atherosclerosis (8 papers, 2017 to 2025). A disease characterized by the build-up of fatty material and calcium deposition in the arterial wall resulting in partial or complete occlusion of the arterial lumen. "In conclusion, we identified one CpG located at AHRR to be associated with common carotid intima-media thickness, a subclinical marker of atherosclerosis." (PMID 34091768, 2021). "In a previous analysis in MESA that used a candidate gene approach to assess the association between CpGs in AHRR and atherosclerosis, hypomethylation at cg05575921 (P = 3.08 × 10−10) and cg21161138 (P = 7.73 × 10−8) was significantly associated with carotid plaque score." (PMID 35039093, 2022). "In a sample of African-Americans, DNA methylation of AHRR, GFI1, and LRRC52 were associated with atherosclerosis after adjusting for cardiovascular diseases risk factors." (PMID 38031118, 2023). "After adjusting for CVD risk factors, four CpGs (cg05575921(AHRR), cg09935388 (GFI1), cg21161138 (AHRR), and cg18168448 (LRRC52)) were associated with multi-site atherosclerosis (FDR < 0.1)." (PMID 35039093, 2022). "A recent study determined that common environmental factors such as cigarette smoke induce DNA hypomethylation of AhRR in subclinical atherosclerosis." (PMID 34884515, 2021). "LINC00305 promotes an interaction between the membrane protein lipocalin-interacting membrane receptor (LIMR) and the inflammatory gene aryl hydrocarbon receptor repressor (AHRR) via activation of the NF-kappaB pathway in human monocytes, further contributing to the development of atherosclerosis." (PMID 30523422, 2018).